CPT1A (carnitine palmitoyltransferase 1A)
Diseases named in the same sentence as CPT1A in open-access papers (continued):
Sharing a sentence is not in itself a finding about the gene and the disease.
breast cancer (continued). "Pre-menopausal breast cancer patients with a high expression level of CPT1A had a higher survival rate than their post-menopausal counterparts." (PMID 36735704, 2023). "We confirmed prior evidence of the paradoxical relationship between obesity and breast cancer and the detrimental nature of CPT1A expression on prognoses." (PMID 36735704, 2023). "This large scope analysis highlights further the potential of CPT-1A as a novel biomarker of breast cancer progression and to our knowledge, is the first study to demonstrate the associations of CPT-1A with immune regulation." (PMID 36180554, 2022). "High expression of CPT-1A in breast cancer patients correlates with a decreased overall survival (p = 0.007) and stage as more advanced breast cancers show higher expression of CPT-1A (p = 0.0035)." (PMID 36180554, 2022). "Overexpression of CPT-1A largely confers a worse prognosis and CPT-1A progressively recruits a range of pathways as breast cancer progresses." (PMID 36180554, 2022). "Genomic alterations in the CPT-1A gene were detected in 9% of breast cancers in the cancer genome atlas (TCGA) and METABRIC cohorts." (PMID 36180554, 2022). "Overall, it emerged that miR-328-3p/CPT1A/fatty acid β-oxidation is responsible for breast cancer development and metastasis." (PMID 36230935, 2022). "In breast cancer, a previous study has shown that miR-328-3p regulates tumor cell stemness by affecting the CPT1A-FAO axis in BRCA cells, thereby playing a pivotal role in BRCA metastasis." (PMID 35692496, 2022). "In this study, utilising a bioinformatic approach, we showed that CPT-1A is a predictive and prognostic marker of a poor outcome in luminal A and luminal B breast cancers." (PMID 36180554, 2022). "When patients were split by molecular subtype, the predictive effect of CPT-1A was shown to occur in luminal A and luminal B breast cancers only (p = 0.028)." (PMID 36180554, 2022). "High grade, poor survival and disease progression result in the association of CPT-1A with additional pathways, implying that CPT-1A recruits additional pathways as breast cancer progresses." (PMID 36180554, 2022). "There are three isoforms of CPT-1; A, B and C. It is CPT-1A that has been shown to be the predominant isoform which is overexpressed in breast cancer." (PMID 36180554, 2022). "In ER and PR-positive breast cancers, there was a tendency for CPT-1A to cluster in the context of under expression." (PMID 36180554, 2022). "Above all, these different lines of evidence led to our investigation of CPT1A as a possible serum biomarker for breast cancer." (PMID 33858374, 2021). "In our study, we found that CPT1A is overexpressed in breast cancer and can be detected in the cell culture medium." (PMID 33858374, 2021). "As a result, in the test set, the AUC of CPT1A in differentiating breast cancer patients from healthy controls was 0.904 (95% CI, 0.869–0.939)." (PMID 33858374, 2021). "In this study, we found that the serum CPT1A level was significantly elevated in 430 breast cancer patients compared with either 200 patients with benign breast disease or 400 healthy controls." (PMID 33858374, 2021). "High level of CPT1A leads to a poor outcome of breast cancer patients according to the TCGA database." (PMID 33858374, 2021). "Beyond the direct effects of CPT1A on tumor cells, it was recently reported that CPT1A is secreted by tumor cells in the blood stream and detected as a serum biomarker for breast cancer diagnosis and progression." (PMID 34638293, 2021). "Although the CPT1A levels in breast cancer patients and healthy controls were significantly different in our study, some overlap was still observed in patients and controls." (PMID 33858374, 2021). "CPT1A is regulated by c-MYC or AMPK in breast cancer, and promotes breast cancer metastasis or therapeutic resistance through several oncogenic signaling pathways, such as VEGF, ERK and Src pathways." (PMID 33858374, 2021).
breast cancer (continued). "Although CPT1A is a mitochondrial protein, it was identified in exosomes of breast cancer cell lines in a study exploring the proteomic profile of extracellular vesicles derived from 60 cell lines of the National Cancer Institute (NCI-60)." (PMID 33858374, 2021). "Then we moved to investigate CPT1A levels in breast cancer tissues, cell lines and cell culture medium." (PMID 33858374, 2021). "In this study, we aimed to identify the clinical significance of CPT1A as a biomarker for the diagnosis and prediction of breast cancer." (PMID 33858374, 2021). "Receiver operating characteristic (ROC) curves were generated, and binary logistic regression analyses were performed to evaluate the effectiveness of CPT1A as a biomarker in breast cancer diagnosis." (PMID 33858374, 2021). "According to previous studies, CPT1A amplification was found in 20% of ER-positive breast cancer cases, and the CPT1A protein level is elevated in most breast cancer cell lines." (PMID 33858374, 2021). "CPT1A expression was found to be closely related to a poor prognosis in prostate cancer, ovarian cancer, Burkitt’s lymphoma, glioblastoma, leukemia, breast cancer, and gastric cancer." (PMID 33528867, 2021). "CPT1A expression levels are also elevated in breast cancer cell lines compared with immortalized mammary epithelial cells." (PMID 33858374, 2021). "Blocking FAO via FAO inhibitor or by CRISPR-mediated CPT1A/CPT2 gene deficiency inhibited radiation-induced ERK activation and aggressive growth and radioresistance of radioresistant breast cancer cells and radiation-derived breast cancer stem cells." (PMID 34217300, 2021). "Western blot, ELISA and in silico analysis were used to confirm CPT1A levels in breast cancer cell lines, cell culture medium and breast cancer tissues." (PMID 33858374, 2021). "Blocking fatty acid oxidation by knocking out CPT1A/CPT2 via CRISPR-mediated has been shown to inhibit the invasive phenotype of radiotherapy-resistant breast cancer, suggesting that CPT2 is a potential metabolic target for breast cancer radiotherapy." (PMID 34740325, 2021). "Our previous study found that CPT1A binds to several vesicular trafficking proteins, and CPT1A was indeed identified in exosomes of breast cancer cell line in another study." (PMID 33858374, 2021). "Analysis showed that serum CPT1A displayed a higher AUC in differentiating breast cancer patients from healthy controls, with a higher and more balanced sensitivity and specificity than the other three tumor markers." (PMID 33858374, 2021). "The threshold value used to classify breast cancer patients into the high and low groups is the median value of CPT1A level in each set." (PMID 33858374, 2021). "By performing a comparison of CPT1A levels in 170 paired serum samples obtained before and after surgery, we found that serum CPT1A levels decreased in breast cancer patients after surgical removal of the tumor." (PMID 33858374, 2021). "Then we analyzed the protein level of CPT1A in cell culture medium of a panel of breast cancer cell lines." (PMID 33858374, 2021). "The median level of CPT1A in serum from breast cancer patients after surgery was 32.16 ± 22.54 ng/mL, which was significantly lower than its level before surgery (45.61 ± 45.89 ng/mL, p < 0.0001)." (PMID 33858374, 2021). "We also found that CPT1A exhibited good efficacy in differentiating patients with breast cancer from patients with benign breast disease (AUC, 0.807; 95% CI, 0.759–0.855)." (PMID 33858374, 2021). "We found that CPT1A levels in cell culture medium are increased in most breast cancer cell lines, especially in TNBC cell lines, compared with immortalized mammary epithelial cells." (PMID 33858374, 2021). "CPT1A levels (23.95 ± 12.70 ng/mL) consistently decreased in post-surgery serum samples of breast cancer patients compared with paired pre-surgery samples (41.40 ± 35.02 ng/mL, p < 0.0001)." (PMID 33858374, 2021).
breast cancer (continued). "As for CPT1A, all breast cancer tissues were characterised by extremely high enzyme expression; however, a slight but significant decrease in H-score was observed in the HR- subtypes—similarly to FASN." (PMID 32899149, 2020). "Breast cancer cells stimulate the depletion of adipocyte triacylglycerols and transfer free FAs to breast cancer cells, increasing CPT1A, resulting in increased proliferation and migration." (PMID 32731620, 2020). "NEAT1 upregulates CPT1A expression by inhibiting miR-107 to promote the progression of breast cancer cells." (PMID 33123488, 2020). "Of note, CPT1A/CPT2 expression was also elevated in human recurrent breast cancer tissues compared to biopsy tumors." (PMID 31803610, 2019). "A doxycycline-inducible breast cancer cell line model overexpressing the rate-limiting enzyme in FAO, carnitine palmitoyl transferase 1A (CPT1A) was generated and analysed to confirm the association between FAO and cancer-associated characteristics in vitro." (PMID 30092766, 2018). "Upregulated expression of CPT1A has also been determined in breast cancer by an integrated genomic strategy based on the use of gene expression signatures of oncogenic pathway activity." (PMID 29445084, 2018). "Breast cancer cells treated with etomoxir to inhibit CPT1A resulted in cell death, while in vivo, mutant KRAS lung tumours were dependent on ACSL3-dependent FAO for tumour initiation and progression." (PMID 30092766, 2018). "In breast cancer, the expression of CPT1A was higher in oestrogen receptor (ER)-positive, compared to ER-negative tumours and cell lines." (PMID 30092766, 2018). "Overexpression of CPT1A - the rate-limiting enzyme in FAO - decreased the proliferation rate of MDA-MB231 breast cancer cells." (PMID 30092766, 2018). "Adipocyte-derived free fatty acids were transferred to breast cancer cells, driving fatty acid metabolism via increased CPT1A and electron transport chain complex protein levels, resulting in increased proliferation and migration." (PMID 28101337, 2017). "On the contrary, genes such as PDGF-A, SERPINB2, TIMP1, which have been associated to poor prognosis, invasion and metastases, were down-regulated in CPT1A silenced breast cancer cells." (PMID 26799588, 2016). "The knockdown of CPT1A variant 2 by small interfering RNAs (siRNAs), was sufficient to induce apoptosis in MCF-7, SK-BR3 and MDA-MB-231 breast cancer cells." (PMID 26799588, 2016). "Recently, we demonstrated that CPT1A was significantly down-regulated in the cytosolic compartment of human colorectal and breast cancer tissues and in several neoplastic cell lines, whereas it showed a peculiar localization in the nuclei of the same samples." (PMID 26799588, 2016). "Western blot analysis of nuclear extracts from MCF7 cancer cells and MCF12F cells, derived from normal mammary gland, confirmed the presence of CPT1A (86kDa) only in the nuclei of breast cancer cells line." (PMID 26799588, 2016). "In marked contrast, in both MCF-7 and MDA-MB-231 breast cancer cells in which CPT1A was knocked down, PRL increased enzyme activity by 10 and 17%, respectively, although levels were not restored to baseline (reflected by treatment with vehicle only)." (PMID 21294903, 2011). "We propose a mechanism by which PRL elicits its effect on CPT1A in representative breast cancer cells." (PMID 21294903, 2011). "It will be of considerable interest to evaluate the contribution of PPARα on changes in CPT1A expression and activity in breast cancer cells in response to PRL in future studies." (PMID 21294903, 2011). "In addition, the expression of CPT1A is increased in ESR-positive breast cancer cell lines, suggesting that ESR likely has a regulatory effect on CPT1A." (PMID 41563994, 2026). "To validate whether RACGAP1 regulated FA metabolism by targeting CPT1A, we successfully overexpressed CPT1A in breast cancer cells transfecting with sh-RACGAP1, and its overexpression exhibited no influences on the expression of RACGAP1." (PMID 41444950, 2025).
breast cancer (continued). "In addition, CPT1A appears to be a candidate therapeutic target in various cancers, including lung cancer, breast cancer, etc.." (PMID 40606607, 2025). "Promoting breast cancer metastases across the USP10/IGF2BP1/CPT1A axis, it may directly identify and bind the m6A site on CPT1A mRNA, hence enhancing its stability." (PMID 39679845, 2024). "CPT1A has been documented to be upregulated in various cancers, including breast cancer." (PMID 39679845, 2024). "We also investigated whether CPT1A expression was implicated as a biomarker of resistance to HER2-targeted therapy, particularly Trastuzumab, in HER2+ breast cancer." (PMID 39097623, 2024). "IGF2BP1 could recognize and bind to the m6A sites on CPT1A mRNA, promoting the N6-methyladenosine modification and breast cancer metastasis." (PMID 39430239, 2024). "In ErbB2+ breast cancer models, ablation of Cpt1a delays tumor onset, growth, and metastasis." (PMID 39097623, 2024). "Using RNA expression data from both microarray and mRNA sequencing, we confirmed that overexpression of CPT1A is a marker of poor prognosis correlating with decreased overall survival in all breast cancer patients (p = 0.0035) and specifically in HER2+ breast tumors (p = 0.00071)." (PMID 39097623, 2024). "In addition, studies have shown that mitochondrial FAO reprogramming is enhanced in breast cancer, and CPT1A expression is elevated in recurrent breast cancer, which is associated with poor prognosis in patients with breast cancer." (PMID 37497413, 2023). "Further, CPT1A is overexpressed in breast cancer tissues compared to normal breast tissues." (PMID 36735704, 2023). "This may suggest that the use of the CPT1a inhibitor etomoxir should be revisited in obese breast cancer patients." (PMID 36732635, 2023). "This suggests that CPT1A inhibition may be a promising therapeutic approach for this particular subtype of breast cancer." (PMID 37033619, 2023). "We employed the Xena Functional Genomics Explorer to understand how CPT1A expression may predict breast cancer prognosis, through the lens of clinical and anthropometric data." (PMID 36735704, 2023). "Thus, we concluded that blocking CPT1a is sufficient to impair the growth of breast cancer cells in the lung environment." (PMID 36732635, 2023). "For instance, the uptake, utilization and enhanced intracellular trafficking of adipocyte-derived FA has been shown to promote breast cancer progression, as well as to be critical in colon cancer, whereby CPT1A-dependent FAO upregulates Wnt/β-catenin signaling by regulating β-catenin acetylation." (PMID 36994106, 2023). "Additionally, we found that CPT1a expression was higher in metastatic samples compared to primary tumor tissue of patients with breast cancer (Expression Project for Oncology - expO, GSE2109)." (PMID 36732635, 2023). "CPT-1A genomic alterations have been detected, in 9% of breast cancers." (PMID 37251324, 2023). "Our data showed that depletion of FDXR inhibited tumor cell growth in T47D and MCF7 breast cancer cell lines, and this phenotype could be at least partially rescued by the reconstitution of CPT1A expression." (PMID 37207154, 2023). "Based on these data, we concluded that CPT1a may be important for breast cancer progression in patients and that breast cancer-derived metastases may rely on CPT1a to process palmitate." (PMID 36732635, 2023). "In summary, fatty acid metabolism with respect to CPT1A was detrimental to breast cancer outcomes." (PMID 36735704, 2023). "Furthermore, the miR-328-3p/CPT1A/fatty acid β-oxidation/stemness axis was shown responsible for breast cancer metastasis." (PMID 34045663, 2022). "CPT1A has been reported to be upregulated in numerous cancers, including breast cancer." (PMID 36233047, 2022).
breast cancer (continued). "Therapeutics that target CPT-1A, originally developed to treat heart disease and diabetes, could be repurposed in the context of breast cancer as a way to achieve sustainable tumour control and as an adjunctive treatment to immunotherapies." (PMID 36180554, 2022). "In addition, inhibiting the expression of CPT1A in prostate cancer, nasopharyngeal carcinoma, breast cancer, or lung adenocarcinoma cells can increase the sensitivity of cancer cells to hormone-blocking chemotherapy or radiotherapy." (PMID 35692496, 2022). "Similarly, HuR and AGAP2-AS interact and stabilize CPT1A (Carnitine Palmitoyltransferase 1A) in mesenchymal stem cells, thereby promoting trastuzumab resistance in breast cancer." (PMID 35884580, 2022). "CPT1A is overexpressed in breast cancer and can be secreted out of breast cancer cell." (PMID 33858374, 2021). "CPT1A was overexpressed in breast cancer tissues, cell lines and cell culture medium." (PMID 33858374, 2021). "We confirmed the expression level of CPT1A in breast cancer tissues, cell lines and culture medium." (PMID 33858374, 2021). "It is also necessary to determine whether serum CPT1A is a specific biomarker of breast cancer only or is also an accurate biomarker for other cancer types." (PMID 33858374, 2021). "Overall, these studies indicated that CPT1A plays an important role in breast cancer progression and could be a promising target in breast cancer." (PMID 33858374, 2021). "Recently CPT1A is emerged as a crucial regulator for breast cancer." (PMID 33858374, 2021). "Thus, the serum CPT1A level was found to be an effective indicator for evaluating the surgical outcome or tumor recurrence of breast cancer patients." (PMID 33858374, 2021). "Our study showed that CPT1A could be released into cell culture medium by breast cancer cells, and serum CPT1A could be employed to distinguish breast cancer patients from healthy controls and assist in the diagnosis of breast cancer." (PMID 33858374, 2021). "In the training set, the AUC of CPT1A in differentiating breast cancer patients from healthy controls was 0.892 (95% CI, 0.872–0.920), and the optimum CPT1A cutoff value was 27.57 ng/mL for breast cancer diagnosis (training set: sensitivity, 75.4%; specificity, 86.1%)." (PMID 33858374, 2021). "Moreover, CPT1A exhibited a higher efficacy in differentiating breast cancer patients from healthy controls (training set: area under the curve, AUC, 0.892, 95% CI, 0.872–0.920; test set, AUC, 0.904, 95% CI, 0.869–0.939) than did CA15–3, CEA, or CA125." (PMID 33858374, 2021). "Inhibition of CPT1A activates cell apoptosis and suppresses cell invasion in breast cancer." (PMID 33858374, 2021). "Thus, components of CS, including CPT1A, appear to be upregulated in low-grade mammary carcinomas and progressively downregulated or less expressed as the tumor becomes more malignant." (PMID 34679988, 2021). "The expression of CPT1A is reportedly regulated by PPARs and the PPARγ coactivator (PGC-1), which is associated with histone deacetylase activity and enhanced tumorigenesis of breast cancer cells." (PMID 32133293, 2020). "First, we surveyed the expression levels of CPT1A in breast cancer tissues and cell lines." (PMID 30092766, 2018). "Furthermore, in silico analysis of gene expression data from a panel of breast cancer cell lines found that CPT1A expression was higher in ER-positive, compared to ER-negative cell lines." (PMID 30092766, 2018). "Interestingly, analysis of 594 TCGA ER+ breast cancer samples showed CPT1A amplification and/or mRNA upregulation in 20% (117/594) of the ER+ breast cancer samples." (PMID 28101337, 2017). "Compared with healthy controls, serum CPT1A level was elevated in patients with benign breast diseases, which indicated that CPT1A might play a significant role in the tumorigenesis and early development of breast cancer." (PMID 33858374, 2021).